CAPNS1 (calpain small subunit 1)
Description:
Regulatory subunit of the calcium-regulated non-lysosomal thiol-protease which catalyzes limited proteolysis of substrates involved in cytoskeletal remodeling and signal transduction. Essential for embryonic development (By similarity).
Synonyms: CSS1; CDPS; CAPN4; CANP; CANPS; 30K; CALPAIN4; PPH6
Tractability: Small molecule: a structure with a bound ligand is known; a high-quality ligand is known; it has a binding pocket of medium quality; it belongs to a druggable protein family. Antibody: its Gene Ontology location is reachable by antibodies, with high confidence; UniProt places it where antibodies can reach, with medium confidence. PROTAC: ubiquitination databases record sites on it; its protein half-life has been measured; a small molecule that binds it is known.
Target class: Cysteine protease C2 family; Cysteine protease; Protease; Enzyme; Cysteine protease CA clan; Cysteine protease C2 regulatory subfamily
Gene: Protein-coding gene on chromosome 19 (36,139,953 to 36,150,356, forward strand). Ensembl gene ENSG00000126247.
Subcellular location: Cytoplasm; Cell membrane
Subcellular location (Human Protein Atlas): Cytosol; Nucleoplasm
Pathways (Reactome):
Cellular responses to stimuli: High laminar flow shear stress activates signaling by PIEZO1 and PECAM1:CDH5:KDR in endothelial cells; Turbulent (oscillatory, disturbed) flow shear stress activates signaling by PIEZO1 and integrins in endothelial cells
Developmental Biology: Formation of the cornified envelope
Disease: Deregulated CDK5 triggers multiple neurodegenerative pathways in Alzheimer's disease models
Extracellular matrix organization: Degradation of the extracellular matrix
Gene Ontology:
Molecular function: calcium-dependent cysteine-type endopeptidase activity; protein binding; calcium ion binding
Biological process: positive regulation of cell population proliferation; proteolysis; regulation of macroautophagy
Cellular component: calpain complex; cytosol; extracellular exosome; membrane; plasma membrane; cytoplasm
Genetic constraint (gnomAD): Loss-of-function variants: 25 observed, 29.44 expected, observed/expected ratio (o/e) 0.85, 90% interval 0.62 to 1.19. The upper end of that interval is the gene's LOEUF score, 1.19, which puts it in group 5 of 6, group 1 being the genes least tolerant of losing a copy. Missense variants: 315 observed, 296.58 expected, observed/expected ratio (o/e) 1.06, 90% interval 0.97 to 1.17. Synonymous variants: 128 observed, 107.02 expected, observed/expected ratio (o/e) 1.2, 90% interval 1.03 to 1.38.
Homologues: Orthologues: macaque CAPNS1 (99% identical), chimpanzee CAPNS1 (98% identical), pig CAPNS1 (96% identical), rabbit CAPNS1 (95% identical), dog CAPNS1 (95% identical), mouse Capns1 (94% identical), rat Capns1 (93% identical), guinea pig CAPNS1 (91% identical), tropical clawed frog capns2 (54% identical), zebrafish capns1a (53% identical), zebrafish capns1b (51% identical), Caenorhabditis elegans clp-8 (20% identical), and 7 more. Paralogues in human: CAPNS2 (63% identical), CAPN3 (47% identical), CAPN1 (43% identical), CAPN2 (42% identical), CAPN11 (38% identical), CAPN9 (38% identical), CAPN8 (38% identical), CAPN12 (34% identical), CAPN13 (28% identical), CAPN14 (26% identical), SRI (22% identical), ADGB (21% identical), and 8 more.
Diseases named in the same sentence as CAPNS1 in open-access papers:
CAPNS1 is named in the same sentence as 53 diseases in open-access papers, as found by Europe PMC text mining. Sharing a sentence is not in itself a finding about the gene and the disease. The quoted sentences say what the papers report.
gastric cancer (6 papers, 2016 to 2022). A primary or metastatic malignant neoplasm involving the stomach. "It has been shown that resistant gastric cancer cells demonstrate upregulated levels of miR-99a and miR-491 gene expression regulators, which are highly associated with drug resistance and CAPNS1 gene downregulation." (PMID 36233276, 2022). "MiR-520b-3p could target epidermal growth factor receptor (EGFR), histone deacetylase 4 (HDAC4) and calpain small subunit 1 (CAPN4) respectively to exert tumor-suppressive effects in gastric cancer, lung cancer, prostate cancer." (PMID 32497020, 2020). "MiR-99a and miR-491, which are also overexpressed in SGC-7901/DDP and BGC-823/DDP resistant gastric cancer cells, could promote DDP resistance by directly down-regulating their target gene, calpain small subunit 1 (CAPNS1)." (PMID 32192494, 2020).
hepatocellular carcinoma (6 papers, 2010 to 2024). A malignant tumor that arises from hepatocytes. "Calpain small subunit 1 (Capn4) has been shown to correlate with the metastasis/invasion of hepatocellular carcinoma." (PMID 23349941, 2013). "Recently, we have reported that HBx promotes hepatoma cell migration through the upregulation of calpain small subunit 1 (Capn4)." (PMID 22355367, 2012). "CAPNS1 is one out of five key prognostic autophagy-related genes in hepatocellular carcinoma." (PMID 38397997, 2024). "Indeed, CAPNS1 expression has been detected in various cancers, including hepatocellular carcinoma, ovarian carcinoma, colorectal cancer, and nasopharyngeal carcinoma." (PMID 35402224, 2022). "CAPNS1 has been explored as a crucial protein that could promote metastasis of hepatocellular carcinoma." (PMID 34869345, 2021).
breast carcinoma (4 papers, 2017 to 2024). "In both MCF7 and MCF10AT cell lines, CAPNS1 depletion leads to the enlargement of the stem cell compartment in breast cancer." (PMID 38397997, 2024). "Capns1 knockdown or knockout in breast carcinoma cells results in markedly decreased migration and invasion in vitro and metastatic activity in vivo in preclinical mouse models." (PMID 32665543, 2020).
COVID-19 (3 papers, 2022 to 2024). A disease caused by infection with severe acute respiratory syndrome coronavirus 2. "Next, given the fact that the heart specimens in T2D patients with COVID-19 are quite heterogeneous, further experiments and efforts to identify Capns1 in mice mimicking SARS-CoV-2 infection appear well justified." (PMID 35242109, 2022). "Furthermore, CAPNS1 was found to play a significant role in regulating platelet activity and thrombosis under hypoxia, a condition commonly seen in severe COVID-19 patients." (PMID 35421970, 2022). "Additionally, the cellular adhesion regulators: calpain small subunit 1 (CAPNS1) and fibulin 5 (FBLN5), were both down-regulated six months after COVID-19." (PMID 39183264, 2024).
liver cancer (2 papers, 2019 to 2022). An epithelial or non-epithelial malignant neoplasm that arises from the liver. "A subsequent multivariate survival analysis identified five key prognostic ARGs (ATIC, BAX, BIRC5, CAPNS1, and FKBP1A) that were used to construct prognostic risk models, which provided an accurate prognosis for patients with malignant liver tumors." (PMID 35402224, 2022). "The results from TCGA database indicated that overexpression of ATIC, BIRC5, BAX, CAPNS1, and FKBP1A was closely related to an inferior OS of patients with liver cancer." (PMID 35402224, 2022).
muscular dystrophy (2 papers, 2023 to 2025). Muscular dystrophy (MD) refers to a group of more than 30 genetic diseases characterized by progressive weakness and degeneration of the skeletal muscles that control movement. "Loss of calpains-1 and -2, by knockout of the shared calpain small subunit 1 (CAPNS1), impairs calcium-dependent membrane repair in cells exposed to mechanical scrape injury, and induces severe muscular dystrophy in mice." (PMID 36653852, 2023).
Obesity (2 papers, 2014 to 2018). Accumulation of substantial excess body fat. "Methylation loci associated with obesity (AEBP2), calcium signaling (CAPNS1), insulin signaling (INSR, PTPRN2, RPTOR) and vasodilation (VASP) also appeared to be epigenome-wide significant." (PMID 29692868, 2018). "In addition to the findings of these immune-regulatory genes, many other top associations have been implicated in obesity (AEBP2) (FDR < 0.10), calcium signaling (CAPNS1), insulin signaling (INSR, PTPRN2, RPTOR), and vasodilation (VASP)." (PMID 29692868, 2018).
schizophrenia (2 papers, 2016 to 2022). A major psychotic disorder characterized by abnormalities in the perception or expression of reality. "Expression of CAPNS1 gene with signal transductions of calcium-dependent activity changes in schizophrenia." (PMID 28117656, 2016). "Furthermore, the most significant proteins for suicide in the WGCNA analysis included CAPNS1 (Calpain Small Subunit 1), which is suggested to play a neuroprotective role, and CSNK2B and PTP4A2, implicated as biomarkers for psychiatric disorders such as major depressive disorder and schizophrenia." (PMID 35383147, 2022).
triple-negative breast carcinoma (2 papers, 2018 to 2025). An invasive breast carcinoma which is negative for expression of estrogen receptor (ER), progesterone receptor (PR), and human epidermal growth factor receptor 2 (HER2). "Therefore, we have generated a panel of CRISPR-Cas9 KO MDA-MB-231 triple-negative breast cancer cell lines for CAPN1, CAPN2, or CAPNS1 genes, which provide models for complete pharmacological inhibition of calpain-1, calpain-2, or both, respectively." (PMID 40940726, 2025).
Aortic dissection (1 paper, 2025). Aortic dissection refers to a tear in the intimal layer of the aorta causing a separation between the intima and the medial layers of the aorta. "In contrast, macrophage‐specific Capns1 knockout does not impact TAD development but accelerates aortic dissection rupture in later stages." (PMID 40171827, 2025).
colon cancer (1 paper, 2020). "For this purpose, we compared the expression levels of CAPN1, CAPN2, CAPNS1 and CAST in different cell lines and chose human HCT116 colon cancer cells." (PMID 33078830, 2020).
diabetic cardiomyopathy (1 paper, 2020). Diabetic cardiomyopathy is a disorder of the heart muscle in people with diabetes. "Endothelial cell-specific deletion of Capns1 reduced diabetic cardiomyopathy by improving angiogenesis." (PMID 32665543, 2020).
glomerulosclerosis (1 paper, 2020). A hardening of the kidney glomerulus caused by scarring of the blood vessels. "Loss of Capns1 in podocytes improves glomerulosclerosis and tubulointerstitial injury in the Gak-KO mice." (PMID 33208557, 2020). "Podocyte-specific deletion of Capns1, essential for calpain-1 and calpain-2 activities, also improved proteinuria and glomerulosclerosis in Gak-KO mice." (PMID 33208557, 2020).
liver disease (1 paper, 2024). "By training random forest models, a biomarker panel comprising KNG1, F11, KLKB1, CAPNS1, CDH1, CPN2, NME2, was identified by feature selection for liver disease detection." (PMID 39207047, 2024).
lymph node metastasis (1 paper, 2022). "In the exosomes from patients with lymph node metastasis, 697 differentially expressed proteins were identified, and overexpressed proteins included SRC, TLN1, integrin β2 subunit, and CAPNS1." (PMID 35406748, 2022).
membranous nephropathy (1 paper, 2023). "Microarray studies have highlighted CAPNS1 as being modulated in membranous nephropathy and in immunoglobulin A nephropathy, while other studies have reported the importance of miR-375 (for which myotrophin MTPN is a target) for glucose homeostasis and as a potential biomarker in type 2 diabetes." (PMID 36769128, 2023).
osteosarcoma (1 paper, 2017). A usually aggressive malignant bone-forming mesenchymal neoplasm, predominantly affecting adolescents and young adults. "We previously showed that CAPNS1 depleted human osteosarcoma U2OS cells and CAPNS1−/− MEFs fail to induce autophagosomes formation in response to nutrient deprivation and rapamycin, the classic autophagy-inducing stimuli." (PMID 28302665, 2017). "We previously demonstrated the requirement of CAPNS1 for autophagosome formation in response to rapamycin in MEFs and human osteosarcoma U2OS cells." (PMID 28302665, 2017). "Upon inhibition of the endoplasmic reticulum Ca2+ ATPase by 100 nM thapsigargin, both micro-calpain and autophagy are activated in human U2OS osteosarcoma cells in a CAPNS1-dependent manner." (PMID 28302665, 2017).
pulmonary hypertension (1 paper, 2020). Increased pressure within the pulmonary circulation due to lung or heart disorder. "In other organ systems, selective loss of Capns1 in the pulmonary artery smooth muscle cells displays a protective effect in pulmonary hypertension and lung damage, suggesting that inhibiting this pathway may provide an avenue for novel therapeutics." (PMID 33208557, 2020).
vitiligo (1 paper, 2022). Generalized well circumscribed patches of leukoderma that are generally distributed over symmetric body locations and is due to autoimmune destruction of melanocytes. "However, the expression of CAPN2 and CAPNS1 in vitiligo needs to be further explored." (PMID 35406685, 2022).
tumor (19 papers, 2012 to 2025). "Amongst them all, they identified calpain small subunit 1 overexpression in the recurrence cohort and that the overexpression was associated with enhanced tumor cell invasiveness in vitro." (PMID 37296890, 2023). "Depletion of CAPN2 or CAPNS1 by knockdown experiments in breast carcinoma cell lines reduced tumor growth in mouse orthotopic xenografts." (PMID 37795261, 2023). "Ablation of the regulatory subunit CAPNS1 in the mammary epithelium delays spontaneous tumor onset in a model of mammary HER2+ tumorigenesis." (PMID 37795261, 2023). "Calpain small subunit 1 (Capn4), a regulatory subunit involved in cell proliferation, migration and apoptosis, is highly correlated with tumour metastasis after liver transplantation." (PMID 35203390, 2022). "CAPNS1 has been reported to play a role in tumor growth and metastasis, and regulates the apoptotic process and proliferation." (PMID 27821810, 2016). "Tumor volumes and weights on excision were also reduced, when mice were injected weekly with siRNA targeting CAPNS1 in combination with 0.1 mg/kg DTX." (PMID 26302712, 2015). "Therefore, we noted the presence of MMP7 and three calpain components, CAPN1, CAPN2, and CAPNS1, as tumor-derived EV protein cargo." (PMID 36470535, 2023). "In contrast, SRC and CAPNS1 were only present in tumor-derived 8305C ectosomes, suggesting that these ectosomes may play an important role in the regulation of integrin-mediated cell adhesion during tumor dissemination." (PMID 35406748, 2022). "By investigating tumor tissues of 232 HCC patients, we identified calpain small subunit 1 (Capn4) as an independent prognostic factor for recurrence and survival in HCC patients after liver transplantation." (PMID 24252133, 2013). "Previous studies demonstrated that tumor cell invasion and metastasis after liver transplantation for HCC was highly correlated with overexpression of calpain small subunit 1 (Capn4), which belongs to the calpain system." (PMID 22355367, 2012). "The possibility that other CAPNS1-independent calpain isoforms could provide redundant functions to potentiate the delayed tumor onset has not been addressed in this study." (PMID 30279968, 2018).
infection (3 papers, 2013 to 2020). The state of being infected such as from the introduction of a foreign agent such as serum, vaccine, antigenic substance or organism. "Infection by Shigella of cells treated with siRNAs against Capns1 or infection of mouse embryonic fibroblasts (MEFs) knock-out for Capns1 (Capns1 KO) similarly failed to trigger a loss in SUMO conjugates when compared to control cells." (PMID 29231810, 2017).
psychiatric disorder (2 papers, 2019 to 2022). A disorder characterized by behavioral and/or psychological abnormalities, often accompanied by physical symptoms. "These miRNAs and mRNAs were previously implicated in psychiatric disorders (miR-320a and SP4), key processes of the central nervous system (CAPNS1, RGS16, SP4) or pathways involved in mental illnesses (miR-155-3p)." (PMID 31801218, 2019).
kidney disease (1 paper, 2020). "Moreover, podocyte-specific deletion of Capns1 in our Gak-KO mice was also associated with reduced kidney disease, further validating our calpain inhibitor studies." (PMID 33208557, 2020).
CAPNS1 also shares sentences with these, for which no sentence is quoted: cancer (13 papers); nasopharyngeal carcinoma (6); prostate carcinoma (4); colorectal cancer (3); glioma (3); lung carcinoma (3); acute kidney injury (2); endotoxemia (2); ovarian carcinoma (2); renal dysfunction (2); Alzheimer disease (1); brachydactyly (1); cholangiocarcinoma (1); endothelial dysfunction (1); esophageal cancer (1); hypertrophy (1); hypothyroidism (1); infarction (1); interstitial lung disease (1); intrahepatic cholangiocarcinoma (1); liver cirrhosis (1); Lymphatic Metastasis (1); major depressive disorder (1); myocardial infarction (1); neuroblastoma (1); non-small cell lung carcinoma (1); steatosis (1); systemic sclerosis (1); type 1 diabetes (1); type 2 diabetes (1).